IYD (iodotyrosine deiodinase)
Description:
Catalyzes the dehalogenation of halotyrosines such as 3-bromo-L-tyrosine, 3-chloro-L-tyrosine, 3-iodo-L-tyrosine and 3,5-diiodo-L-tyrosine. During thyroid hormone biosynthesis, facilitates iodide salvage by catalysing the oxidative NADPH-dependent deiodination of the halogenated by-products of thyroid hormone production, monoiodotyrosine (L-MIT) and diiodotyrosine (L-DIT). The scavanged iodide can then reenter the hormone-producing pathways. Acts more efficiently on 3-iodo-L-tyrosine than 3,5-diiodo-L-tyrosine.
Synonyms: IYD-1; C6orf71; DEHAL1; dJ422F24.1; TDH4
Tractability: Small molecule: a structure with a bound ligand is known. Antibody: UniProt places it where antibodies can reach, with high confidence; its Gene Ontology location is reachable by antibodies, with high confidence; UniProt predicts a signal peptide or a membrane-spanning region; the Human Protein Atlas places it where antibodies can reach.
Safety:
Unwanted effects reported when the protein is acted on. In parentheses: how it was acted on, where the effect was seen, and who reports it.
Altered, Amphibian metamorphosis (inhibition; source: AOP-Wiki)
Gene: Protein-coding gene on chromosome 6 (150,368,892 to 150,405,969, forward strand). Ensembl gene ENSG00000009765.
Subcellular location: Cell membrane; Cytoplasmic vesicle membrane
Subcellular location (Human Protein Atlas): Plasma membrane
Pathways (Reactome):
Metabolism: Thyroxine biosynthesis
Gene Ontology:
Molecular function: FMN binding; iodotyrosine deiodinase activity; protein binding; oxidoreductase activity
Biological process: thyroid hormone metabolic process
Cellular component: cytoplasmic vesicle membrane; plasma membrane
Genetic constraint (gnomAD): Loss-of-function variants: 25 observed, 30 expected, observed/expected ratio (o/e) 0.83, 90% interval 0.61 to 1.16. The upper end of that interval is the gene's LOEUF score, 1.16, which puts it in group 5 of 6, group 1 being the genes least tolerant of losing a copy. Missense variants: 352 observed, 376.41 expected, observed/expected ratio (o/e) 0.94, 90% interval 0.86 to 1.02. Synonymous variants: 140 observed, 138.6 expected, observed/expected ratio (o/e) 1.01, 90% interval 0.88 to 1.16.
Homologues: Orthologues: dog IYD (88% identical), pig IYD (87% identical), guinea pig Iyd (85% identical), mouse Iyd (84% identical), rat Iyd (83% identical), chimpanzee IYD (82% identical), macaque IYD (81% identical), rabbit IYD (80% identical), tropical clawed frog iyd (70% identical), zebrafish iyd (66% identical), Drosophila melanogaster Iyd (48% identical), Caenorhabditis elegans sup-18 (36% identical).
Diseases named in the same sentence as IYD in open-access papers:
IYD is named in the same sentence as 16 diseases in open-access papers, as found by Europe PMC text mining. Sharing a sentence is not in itself a finding about the gene and the disease. The quoted sentences say what the papers report.
hypothyroidism (5 papers, 2021 to 2025). Abnormally low levels of thyroid hormone. "To continue this study, we investigated the dual function of IYD in hypothyroidism by blocking IYD and in thermogenesis by looking at the induction of brown adipocyte-like cells by treatment with H3 Ab in a mouse model." (PMID 35887180, 2022). "H3 Ab has already been shown to inhibit the function of the enzyme, IYD, and these new data suggest this inhibition contributes to body weight gain characteristic of hypothyroidism." (PMID 35887180, 2022). "Collectively, these results suggest that H3 Ab blocks the function of IYD and plays a major role in hypothyroidism metabolism." (PMID 35887180, 2022). "To continue this study, here, we investigated the dual function of IYD in hypothyroidism by blocking IYD and in thermogenesis by looking at the induction of brown adipocyte-like cells by H3 Ab treatment in a mouse model." (PMID 35887180, 2022).
Thyroid dyshormonogenesis (5 papers, 2014 to 2022). "Thyroid dyshormonogenesis usually is caused by single gene mutations, encoding globulins involved in TH synthesis (thyroid peroxidase - TPO, thyroglobulin - TG, Na+/I- symporter – SCL5A5/NIS, pendrine – SCL26A4/PDS), or directly influencing TH synthesis and metabolism (DUOX2, DUOX2A, IYD/DEHAL1)." (PMID 35832434, 2022).
breast carcinoma (3 papers, 2020 to 2025). "These analyses also allow us to identify features that help stratify difficult to treat breast cancer subtypes, i.e., GALP, IYD, and PARP12 were all significantly associated with survival in non-senior triple-negative breast cancer patients." (PMID 32241256, 2020). "Analysis of breast cancer gene expression data from the TCGA database revealed that the expression of AIMP2 and IYD was elevated in breast cancer tissues, whereas the expression of QARS1 was elevated in normal tissues." (PMID 40493339, 2025). "Compared with that in normal breast cells, AIMP2 expression was high in breast cancer cells, whereas QARS1 expression was low in breast cancer cells; the expression of IYD was not clear." (PMID 40493339, 2025).
Pendred syndrome (3 papers, 2013 to 2020). Pendred syndrome (PDS) is a clinically variable genetic disorder characterized by bilateral sensorineural hearing loss and euthyroid goiter. "Mutations in SLC26A4 (strong support) or IYD (strong support) cause Pendred syndrome (OMIM ID 274600) or iodotyrosine deiodinase deficiency, respectively (OMIM ID 274800)." (PMID 23950964, 2013). "Interestingly we detected no causative DEHAL1/IYD or SLC26A4/PDS variants, suggesting that these may be rarely responsible for CH due to DH, depending usually on iodine uptake or associated with syndromic features as in the case of Pendred syndrome." (PMID 33692749, 2020).
thyroid (3 papers, 2016 to 2023). "Inhibition of iodotyrosine deiodinase activity by bromotyrosine (a by-product of leukocyte activation) may contribute to thyroid abnormalities that are associated with systemic inflammation." (PMID 26638695, 2016). "The 11 selected thyroid-specific RNA transcripts (TPO, TG, GFRA2, IYD, PDE8B, WDR86, C16orf89, DGKI, DIO2, TSHR, and PAX8) were amplified from healthy volunteers and thyroid patients." (PMID 34512731, 2021).
hepatocellular carcinoma (2 papers, 2021 to 2022). A malignant tumor that arises from hepatocytes. "IYD encodes iodotyrosine deiodinase, which reportedly has a suppressive effect on hepatocellular carcinoma cells by inhibiting cell glycolysis." (PMID 36158645, 2022).
renal carcinoma (1 paper, 2022). A carcinoma arising from the epithelium of the renal parenchyma or the renal pelvis. "Thus, this study selected IYD, ACADSB, and PSAT1 for validation since they had not been validated in renal cancer tissues and cell lines." (PMID 36118874, 2022).
cancer (5 papers, 2020 to 2025). A tumor composed of atypical neoplastic, often pleomorphic cells that invade other tissues. "CHI3L1 is primarily expressed in epithelial cells, followed by CAFs and myeloid cells, and IYD is specifically expressed in cancer epithelial cells, with minimal expression in other cells." (PMID 39512680, 2024). "The expressions of GLS and NQO1 were significantly higher in TCGA and ICGC cancer tissues, while IYD expression was significantly lower in HCC tissues compared with normal tissues." (PMID 36582227, 2022). "The results of RT-PCR in tissues demonstrated that IYD, ACADSB, and PSAT1 had significantly lower expression levels in cancer tissues than in adjacent tissues, consistent with the predicted results." (PMID 36118874, 2022). "The expression pattern and functional role of IYD in cancers are not known." (PMID 32576292, 2020).
tumor (5 papers, 2016 to 2025). "The findings revealed notable enrichment of AIMP2 and IYD in tumour cells, whereas QARS1 was enriched in immune cells." (PMID 40493339, 2025).
IYD also shares sentences with these, for which no sentence is quoted: congenital hypothyroidism (5 papers); Obesity (1); selenium deficiency (1); thyroid cancer (1); thyroid dysgenesis (1); thyroid tumor (1); triple-negative breast carcinoma (1).